DCAF1 (DDB1 and CUL4 associated factor 1)
Diseases named in the same sentence as DCAF1 in open-access papers (continued):
Sharing a sentence is not in itself a finding about the gene and the disease.
autism (1 paper, 2022). Persistent deficits in social interaction and communication and interaction as well as a markedly restricted repertoire of activity and interest as well as repetitive patterns of behavior. "Taken together, this suggests that the de novo DCAF1 variant may be a newly identified molecular cause of autism and intellectual disability." (PMID 35743672, 2022).
non-small cell lung carcinoma (1 paper, 2025). A group of at least three distinct histological types of lung cancer, including non-small cell squamous cell carcinoma, adenocarcinoma, and large cell carcinoma. "To extend our understanding of the overall cellular function and possibly the effect of OICR-41103 on the potential tumorigenesis activity of DCAF1, we compared the effects of DCAF1 knockdown and OICR-41103 treatment in Non-Small Cell Lung Cancer (NSCLC) cells." (PMID 40683980, 2025).
ovarian carcinoma (1 paper, 2017). A malignant neoplasm originating from the surface ovarian epithelium. "To identify the roles of CUL4-DDB1 E3 ligase complex in ovarian cancer cells, we performed a knockdown of CUL4-DDB1 E3 ligase components, ring of cullin-1 (ROC1), DDB1, or DDB1/CUL4-associated factor-1 (DCAF1) in A2780 cells, and detected 5hmC levels by dot-blot assays." (PMID 29156803, 2017).
ovarian insufficiency (1 paper, 2023). "The silencing of this protein, as well as deletion of DCAF1, determines oocyte loss and ovarian insufficiency." (PMID 37106439, 2023).
schwannoma (1 paper, 2020). A benign, usually encapsulated slow growing tumor composed of Schwann cells. "We also showed that DCAF1 expression was increased in Merlin-deficient schwannoma tissue compared to normal nerve, suggesting that the loss of Merlin leads to the accumulation of DCAF1 protein." (PMID 32629964, 2020). "This novel mechanism could explain why DCAF1 knockdown leads to reduced pERK1/2 levels in Merlin-deficient schwannoma, and why combined shRNA knockdown of DCAF1 and KSR1 reduced the proliferation of schwannoma cells." (PMID 32629964, 2020).
schwannomatosis (1 paper, 2023). The least frequent form of the rare genetic disorder neurofibromatosis. "In addition to functional differences associated with NF2 versions lacking exons 2–3, several patient-derived NF2 related-schwannomatosis NF2 missense mutations within the N-terminal FERM domain were found which impaired NF2 interactions with DCAF1." (PMID 37280085, 2023).
tumor (18 papers, 2013 to 2025). "DCAF1 is also implicated in tumor development, with overexpression observed in lung, breast, bladder, high-grade serous ovarian, and prostate cancers." (PMID 40683980, 2025). "Merlin inhibits CRL4-DCAF1 by directly binding to the DCAF1 substrate recruitment domain, and therefore, Merlin-deficient tumours have increased CRL4-DCAF1 activity." (PMID 32629964, 2020). "We initially examined DCAF1 mRNA expression in 26 pairs of tumor and adjacent peritumor tissues from HCC patients using qRT-PCR." (PMID 38711082, 2024). "The results indicate that both inhibiting DCAF1 and using the Akt inhibitor effectively hinder tumor growth, and their combined application synergistically suppress tumor growth." (PMID 38711082, 2024). "Subsequently, in vitro and in vivo experiments were conducted to explore the function of DCAF1 in tumor growth and metastasis in HCC." (PMID 38711082, 2024). "Knockdown of DCAF1 inhibited tumor proliferation and metastasis and promoted tumor apoptosis, whereas overexpressing DCAF1 yielded opposite effects." (PMID 38711082, 2024). "Quantitative real-time PCR, Western blot and immunostaining were used to determine DCAF1 expression in tumor tissues and cell lines." (PMID 38711082, 2024). "DCAF1-mediated EZH2T367p is oncogenic because DCAF1 knockdown or inhibition reactivates a large set of tumor suppressor genes and impedes cancer cell proliferation." (PMID 37069142, 2023). "In this regard, we observed that the levels of DCAF1 and EZH2T367p are well correlated with each other in the majority of tumor samples." (PMID 37069142, 2023). "This study revealed a fundamental requirement of DCAF1 for activation-induced cell growth and cell cycle entry and showed that interfering with DCAF1 led to defective expansion of both T cells and tumour cells." (PMID 26728942, 2016). "We also found that the combined application of DCAF1 knockdown and Akt inhibitor could significantly suppress subcutaneous xenograft tumor growth." (PMID 38711082, 2024). "Furthermore, expression of Ki67 and DCAF1 in the tumor tissues was detected by IHC staining, and H-Score was then calculated." (PMID 38711082, 2024). "Similarly, in the public dataset GSE63898, there was a significant increase in DCAF1 mRNA level in tumor tissues compared to non-tumor tissues." (PMID 38711082, 2024). "Furthermore, a subcutaneous tumor model was generated to investigate the suppressive effects of the Akt inhibitor combined with DCAF1 knockdown on tumors." (PMID 38711082, 2024). "The expression levels of DCAF1 and PARD3 in the tumor tissues of HCC patients (n = 20) were detected by IHC." (PMID 38711082, 2024). "Interestingly, the mainly nuclear expressed E3 ligase receptor, DCAF1, a part of the CRLDCAF1 and EDVP complex, showed similar tumor essentiality in the test set to DDB1." (PMID 38177131, 2024).
cancer (15 papers, 2016 to 2025). A tumor composed of atypical neoplastic, often pleomorphic cells that invade other tissues. "Although these data clearly linked DCAF1-mediated H2AT120p to epigenetic gene inactivation in cancer cells, one of the remaining questions is whether phosphorylation of non-histone proteins is also critical for DCAF1-promoted oncogenic events." (PMID 37069142, 2023). "In the future, it will be interesting to determine what degree DCAF1 oncogenic activity is dependent on EZH2T367p and H2AT120p in different types of cancer, and how those two epigenetic processes may underlie a key mechanism during uncontrolled cell proliferation and rapid cell growth." (PMID 37069142, 2023). "DCAF1 is expressed at elevated levels in a variety of cancers and promotes cancer progression and metastasis through multiple signaling pathways." (PMID 40164592, 2025). "This study identified DCAF1 as a new cellular glucose sensor and uncovered new insights into mechanism of DCAF1-mediated inactivation of Rheb-mTORC1 pathway for promoting cancer cell survival in response to glucose deprivation." (PMID 38862475, 2024). "VprBP (also known as DCAF1) is a recently identified kinase that is overexpressed in cancer cells and serves as a major determinant for epigenetic gene silencing and tumorigenesis." (PMID 37041410, 2023). "DCAF1-mediated EZH2T367p stimulates cancer cell growth via an accumulation of EZH2 protein and an activation of EZH2 enzymatic activity catalyzing H3K27me3." (PMID 37069142, 2023). "In DCAF1-depleted SW620 cancer cells, ectopic EZH2 wild type and EZH2T367A phospho-blocking mutant showed low stead-state protein levels and minimal growth stimulatory effects." (PMID 37069142, 2023). "More intriguingly, much lower levels of EZH2 were detected in DCAF1-depleted SW620 cancer cells compared to mock-depleted control cells, and the observed reduction of EZH2 correlated well with the disappearance of EZH2T367p." (PMID 37069142, 2023). "A role for DCAF1-mediated H2AT120p in cancer development is further supported by the observation that DCAF1 expression and H2AT120p levels are higher in several cancer types, especially colon cancer." (PMID 37069142, 2023). "Blocking DCAF1-mediated EZH2T367p is another critical process for cancer cell response to the DCAF1 inhibitor B32B3." (PMID 37069142, 2023). "Regarding DCAF1 functions, our gene expression profiling established gene-selective corepressor function of DCAF1 specifically targeting and silencing growth regulatory genes in cancer cells." (PMID 37069142, 2023). "Also, kinase-dead mutations almost completely abolished the transrepression potential of DCAF1 in cancer cells, implying H2AT120p-dependent mechanism for DCAF1 function in maintaining inactive chromatin states and inducing oncogenic transformation." (PMID 37069142, 2023). "DCAF1/VprBP contributes to epigenetic gene inactivation and cancer development." (PMID 37069142, 2023). "Having established a role for DCAF1-mediated EZH2T367p in driving oncogenic gene silencing program, we next asked whether chemical inhibition of DCAF1 would affect EZH2T367p and cancer cell growth." (PMID 37069142, 2023). "Therefore, DCAF1 is central to the critical steps towards aberrant cell expansion and thus could be a useful therapeutic target for treating inflammation and cancer." (PMID 26728942, 2016). "To test this, we depleted DCAF1 and EZH2 in SW620 cancer cells overexpressing DCAF1 and EZH2 by using a lentiviral shRNA infection system." (PMID 37069142, 2023). "Consistent with this mechanistic role, DCAF1-mediated EZH2 phosphorylation leads to elevated levels of H3K27me3 and altered expression of growth regulatory genes in cancer cells." (PMID 37069142, 2023). "A recent study has demonstrated that DCAF1 phosphorylates the T367 site of EZH2 to enhance its nuclear stability and enzymatic activity in colon cancer cells, resulting in elevated H3K27me3 levels and altered growth-regulating gene expression in cancer cells." (PMID 40164592, 2025).
cancer (continued). "Such DCAF1-mediated EZH2 phosphorylation followed by nuclear localization led to elevated levels of H3K27me3 and altered expression of growth regulatory genes in cancer cells." (PMID 40289112, 2025). "Given that the mimicking mutant alone is also sufficient to inactivate growth regulatory genes in DCAF1-depleted cancer cells, DCAF1 seems to rely more heavily on EZH2T367p rather than on H2AT120p in driving colonic tumorigenesis." (PMID 37069142, 2023). "Thus, investigating the function of DCAF1 in non-histone modifications should provide greater insights into oncogenic signaling pathways and more effective strategies for tackling colon and other cancers." (PMID 37069142, 2023).
infection (15 papers, 2008 to 2025). The state of being infected such as from the introduction of a foreign agent such as serum, vaccine, antigenic substance or organism. "Sequential transfection and infection experiments were performed to determine the impact of DCAF1 depletion on cells infected with VprWT or control viruses." (PMID 39975144, 2025). "Other work found HIV-1 Vpr to enhance hMDDC infection in a DCAF1-dependent manner by increasing HIV-1 LTR-driven gene expression rather than influencing HIV Env processing." (PMID 39205287, 2024). "The decreases in abundance observed for HELLS/SMARCA6, RECQL4, SQSTM1/p62, and DCAF1 during Ad5 WT infection were mitigated during AdΔE4 infection, suggesting that manipulation of these proteins is dependent on one or more E4 gene products." (PMID 34463575, 2021). "The immunoblot data also show that HELLS/SMARCA6, RECQL4, SQSTM1/p62, and DCAF1 each exhibit decreased protein abundances during Ad5 WT infection, consistent with the WCP data." (PMID 34463575, 2021). "The WCP data suggest that each of the selected proteins (HELLS/SMARCA6, RECQL4, SQSTM1, and DCAF1) are decreased during Ad5 WT infection, with distinct abundance change profiles." (PMID 34463575, 2021). "This category was the most highly enriched cellular process at 48 hpi, and DCAF1 is an example of a protein that was decreased exclusively at the latest infection time point (48 hpi)." (PMID 34463575, 2021). "Infection with AdΔE4 allowed us to implicate a significant role for the E4 cassette in the degradation of the host factors DCAF1, RECQL4, SMARCA6, and SQSTM1." (PMID 34463575, 2021). "Surprisingly, most histone PTMs, including γH2A.X, only exhibited an ~20–50% reduction following infection with VprQ65R or VprH71R viruses compared to VprWT, suggesting that Vpr utilizes both DCAF1-dependent and - independent mechanisms to modulate DDR signaling and histone PTMs." (PMID 39975144, 2025). "Together, these results demonstrate that SIV Vpx mutants bearing the Q76A point mutation, which specifically blocks the recruitment of DCAF1, are defective in degrading endogenous SAMHD1 and are attenuated during spreading infections in cultured activated PBMC compared to their WT counterparts." (PMID 25996507, 2015). "Because Vpr and DCAF1 are required for Env stability and virion incorporation, we sought to address whether Vpr increases T lymphocyte infection by increasing virion infectivity." (PMID 26186441, 2015). "In addition, Q76A Vpx mutant was still able to substantially rescue IFN-treated MDDC infection, although it was unable to bind DCAF1 and induce SAMHD1 degradation." (PMID 24782834, 2014). "This work demonstrates that the activities of Vpx to overcome restrictions in culture in vitro are also likely to be important for establishment of infection in vivo and suggest that both the nuclear localization and DCAF1-interaction functions of Vpx are critical in vivo." (PMID 22531456, 2012). "Vpx and SIV Vpr assemble with DCAF1 (also known as VPRBP) a substrate receptor for Cullin 4 CRL (Cullin Ring ubiquitin ligase) and target SAMHD1 for degradation, allowing for productive infection to occur." (PMID 37766341, 2023). "Here we demonstrate that Vpr and its cellular co-factor, DCAF1, are necessary for efficient cell-to-cell spread of HIV-1 from macrophages to CD4+ T lymphocytes when there is inadequate cell-free virus to support direct T lymphocyte infection." (PMID 26186441, 2015). "We found that conditioned medium from MDM silenced for DCAF1 did not suppress infection of activated primary T lymphocytes." (PMID 26186441, 2015). "Vpr promotes HIV-1 replication in NKR cells from the 2nd round of infection, likely by overcoming an early block; and its activity does not require DCAF1 and G2 arrest." (PMID 23134572, 2012).
infection (continued). "The partial reduction in DCAF1 levels did not affect the infection of the HIV-1 Vpr+ and HIV-1 Vpr+, suggesting that the Vpr-mediated enhancement of infection in HuT/CCR5 cells did not involve the recruitment of the DCAF1/DDB1/Cul4A complex and proteasomal degradation." (PMID 22570689, 2012).
DCAF1 also shares sentences with these, for which no sentence is quoted: melanoma (4 papers); gastric cancer (2); lung carcinoma (2); Pancreatic Cancer (2); Autoimmunity (1); breast tumor (1); Cockayne syndrome A (1); colon (1); diabetes (1); experimental autoimmune encephalomyelitis (1); gallbladder cancer (1); hepatocellular carcinoma (1); Intellectual disability (1); ischemic stroke (1); latent infection (1); myasthenia gravis (1); Premature ovarian insufficiency (1); renal cell carcinoma (1); sarcoma (1); Stroke (1).